IL17A (interleukin 17A)
Diseases named in the same sentence as IL17A in open-access papers (continued):
Sharing a sentence is not in itself a finding about the gene and the disease.
myocarditis (continued). "Interestingly, while the secretion of IL-17A by Th17 cells may not contribute to the severity of CVB3-induced myocarditis, it plays a role in the development of DCM." (PMID 37175422, 2023). "However, knocking out IL-17A did not ameliorate the severity of myocarditis in IFN-γ-deficient mice, and the IL-17-deficient mice developed almost the same degree of myocarditis as the wild-type controls, suggesting that Th17 is dispensable in acute myocarditis." (PMID 32269577, 2020). "IL-17A, but not IFNγ, has been shown to promote remodeling and fibrosis and progression from acute myocarditis to chronic myocarditis and DCM in the CVB3 and experimental autoimmune models of myocarditis in male mice and in male patients with myocarditis." (PMID 31551929, 2019).
vitiligo (77 papers, 2011 to 2025). Generalized well circumscribed patches of leukoderma that are generally distributed over symmetric body locations and is due to autoimmune destruction of melanocytes. "In the present study, we aimed to investigate the association of X-box Binding Protein 1 (XBP1) and Interleukin-17A (IL-17A) polymorphisms and monitor their systemic as well as skin expression levels in vitiligo patients from Gujarat population in India." (PMID 35046957, 2021). "We have previously shown that IFN-γ and IL-17A, which have also been reported as possible causative cytokines in vitiligo development, inhibited GPNMB expression." (PMID 34639184, 2021). "Distribution of genotype and allele frequencies of XBP1 rs2269577, IL17A rs2275913 and IL17A rs8193036 polymorphisms in vitiligo patients and controls." (PMID 35046957, 2021). "Distributions of genotype and allele frequencies of XBP1 rs2269577, IL17A rs2275913 and IL17A rs8193036 polymorphisms in different subsets of vitiligo patients and controls." (PMID 35046957, 2021). "IL-17 is an emerging target for inflammatory skin disorders, and immunohistochemical analysis has revealed the presence of IL-17 A in both psoriatic and vitiligo lesions, suggesting a pathogenic role of IL17 also in this disorder." (PMID 32635380, 2020). "IFN-γ and IL-17A, two cytokines with possible causal roles in vitiligo development, inhibited GPNMB expression in vitro." (PMID 32188902, 2020). "Additionally, IL-17A has been shown to antagonize melanogenesis and promote melanocyte apoptosis, two mechanisms causing depigmentation in vitiligo." (PMID 37680638, 2023). "Hence, in this study, we aimed to investigate the involvement of XBP1 and IL-17A in vitiligo susceptibility in Gujarat population." (PMID 35046957, 2021). "Moreover, we provided evidences that IFN-γ and IL-17A, two cytokines with possible causal roles in vitiligo development, inhibited GPNMB expression in vitro." (PMID 32188902, 2020). "Another study demonstrated a relationship between the production of pro- and anti-inflammatory cytokines (IL-17A, IL-10, and IL-12p70) by DCs in both stable and active patients with vitiligo." (PMID 35884944, 2022). "Several other studies have also reported a significant increase in IL-17A levels in the skin as well as blood samples of vitiligo patients." (PMID 35046957, 2021). "We evaluated the relationship between serum levels of IL-17A and the clinicopathological characteristics of Vietnamese vitiligo patients." (PMID 33968147, 2021). "One study found that the peripheral blood T-helper type 17 reaction was unbalanced in patients with vitiligo, and the plasma levels of IL-17A and IL-22 were higher healthy controls, which was consistent with our results." (PMID 33679890, 2021). "Another study showed a positive link between serum IL-17A levels and the area of vitiligo lesions, indicating that Th17 cells are involved in the progression of vitiligo." (PMID 35046957, 2021). "Mounting evidence supports the importance of autoreactive T cells and, particularly interleukin-17A- (IL-17A-) secreting Th17 cells, in vitiligo." (PMID 33968147, 2021). "A significant increase in IL17A gene expression was observed in PBMCs of patients with generalized and active vitiligo." (PMID 35046957, 2021). "Higher serum levels of IL-17A in patients with progressive vitiligo and leukotrichia suggest a potential role of IL-17A in melanocyte destruction in the epidermis and the follicular matrix." (PMID 33968147, 2021). "Gene expression analysis revealed that sXBP1 and IL17A levels were significantly higher in PBMCs of generalized (p=0.030 and p=0.039, respectively) and active (p=0.024 and p=0.017, respectively) vitiligo patients." (PMID 35046957, 2021). "A significant increase in IL17A transcript levels in PBMCs of generalized and active vitiligo led us to monitor the expression of IL-17A in the skin of vitiligo patients and controls." (PMID 35046957, 2021).
vitiligo (continued). "Patients with progressive vitiligo had significantly higher IL-17A levels than patients with stable vitiligo (P = 0.014) or healthy individuals (P = 0.002)." (PMID 33968147, 2021). "The gene expression analysis revealed a significant increase in IL17A transcript levels in PBMCs of vitiligo patients as compared to controls." (PMID 35046957, 2021). "The analysis based on the type and activity of vitiligo revealed a significant increase in IL17A transcript levels in PBMCs of patients with generalized and active vitiligo." (PMID 35046957, 2021). "Overall, these findings suggest XBP1 and IL17A play an important role in vitiligo and further substantiate the involvement of ER stress in exacerbating immune-mediated vitiligo pathogenesis." (PMID 35046957, 2021). "We evaluated the correlation between IL-17A levels and clinical characteristics including leukotrichia, disease duration, vitiligo activity, and body surface area involvement." (PMID 33968147, 2021). "It has been proven that serum IL-17 levels and tissue IL-17A mRNA levels of skin biopsies are elevated in vitiligo patients." (PMID 32267311, 2020). "We were impressed, therefore, to find that both of vitiligo-associated IFN-γ and IL-17A downregulated keratinocyte-GPNMB." (PMID 32188902, 2020). "Failure of both TNF-α inhibitors and IL-17A-blockers in alopecia areata and vitiligo limits the involvement of these cytokines in the immune-mediated destruction of skin cells." (PMID 31440261, 2019). "Double immunofluorescencestaining of IL-17A and IL-17RA was performed to identify receptor bound IL-17A.We observed that 50–60% of IL-17RA positive cells are also IL-17Apositive in leading edge vitiligo biopsies." (PMID 21541348, 2011). "In this study, we provided direct tissue evidence forTh17 involvement in vitiligo, manifested by elevated IL-17A mRNA levels and thepresence of IL-17A+ T cells in the leading edge of vitiligo biopsies." (PMID 21541348, 2011). "Th17 polarization of T helper cells in vitiligo was assessed by qPCR analysis ofmRNA levels of IL-17A." (PMID 21541348, 2011). "Despite empirical evidence affirming elevated circulating interleukin-17 (IL-17) levels and increased Th17 lymphocyte counts in vitiligo patients, along with heightened expression levels of IL-17A messenger RNA in vitiligo lesions, the precise role of IL-17 remains elusive." (PMID 38139134, 2023). "Interestingly, the levels of anti-inflammatory DC (CD11b+) and anti-inflammatory cytokine IL-10 were decreased in patients with active vitiligo, in contrast to an increased level of the pro-inflammatory cytokine IL-17A." (PMID 35884944, 2022). "Furthermore, serum IL-17A levels were negatively correlated with age (r = −0.39, P = 0.004) and age of onset (r = −0.33, P = 0.016) in vitiligo patients." (PMID 33968147, 2021). "In the present study, we did not observe a significant association of IL17A rs2275913 and rs8193036 polymorphisms with vitiligo predisposition in Gujarat." (PMID 35046957, 2021). "More studies are needed to understand the role of IL-17A in early onset vitiligo." (PMID 33968147, 2021). "XBP1 rs2269577 G/C, IL17A rs2275913 G/A and IL17A rs8193036 C/T polymorphisms were genotyped by Polymerase Chain Reaction-Restriction Fragment Length Polymorphism (PCR-RFLP) method in 312 controls and 276 vitiligo patients." (PMID 35046957, 2021). "Hence, we estimated the IL-17A protein levels in suction-induced blister fluid (SBF) samples of vitiligo patients and controls." (PMID 35046957, 2021). "Moreover, we observed a significantly elevated sXBP1 expression (p=0.037) as well as IL-17A protein levels (p=0.009) in perilesional skin of vitiligo patients as compared to controls." (PMID 35046957, 2021). "In conclusion, this study provides evidence of that IL-17A may play a crucial role in the induction of vitiligo along with other factors, namely, the genetics, environment, and inflammatory cytokines." (PMID 33968147, 2021).
vitiligo (continued). "Nevertheless, the role of IL-17A in vitiligo remains poorly understood." (PMID 33968147, 2021). "The elevated IL-17A levels in the perilesional skin of vitiligo patients might be as a result of IL-17A secreting Th17 cells infiltrating the vitiliginous lesions." (PMID 35046957, 2021). "Consistent with previous findings, we found that IL-17A levels were correlated with progressive vitiligo, suggesting that IL-17A might be involved in vitiligo induction and progression." (PMID 33968147, 2021). "We also see significant colocalization of IL-17A and IL-17 receptor A inleading edge vitiligo skin." (PMID 21541348, 2011). "Moreover, the higher amount of IL-17A positive cells in the anti-PD-1 therapy-dependent vitiligo may indicate that Th17 cells in the skin lesion could be a distinctive feature of vitiligo as an irAE." (PMID 37680638, 2023). "Moreover, other cell types could express IL-17A, such as NK cells or γ/δ T cells further sustaining a role for innate immunity in vitiligo pathogenesis." (PMID 37680638, 2023). "In addition, IL-17A/F and IL-22 secretion from Th17 cells could increase production of chemokines and cytokines in vitiligo." (PMID 36187493, 2022). "In addition, we report an increased XBP1 splicing and IL17A expression in vitiligo patients." (PMID 35046957, 2021). "In addition, serum IL-17A levels of patients with progressive vitiligo (median 4.35 (2.78–32.26) pg/mL) were significantly higher than those with stable vitiligo (median 2.26 (1.94–6.32) pg/mL, P = 0.014) as well as healthy controls (median 2.66 (1.85–4.79) pg/mL, P = 0.002)." (PMID 33968147, 2021). "This suggests that IL-17A may contribute to the immune response in early-onset vitiligo." (PMID 33968147, 2021). "In the subgroup analysis of active vitiligo, we also could not find the association between affected body surface area and the concentration of IL-17A (r = −0.15, P = 0.38)." (PMID 33968147, 2021). "Compared with pretreatment psoriatic lesions, posttreatment vitiligo lesions displayed higher staining levels of CD8, IFN-γ, and CXCL10, whereas staining levels of IL-17A and TNF-α were lower." (PMID 40861456, 2025). "Indeed, AhR expression was significantly lower in CD4+ T cells and the skin of vitiligo patients than that in healthy controls, and knockdown of AhR increased IL-17A production and decreased IL-22 levels in CD4+ T cells of vitiligo patients." (PMID 35625824, 2022). "Furthermore, IFN-γ, IL-17A, and oxidative stress dampened the GPNMB expression in vitiligo keratinocytes." (PMID 34639184, 2021). "In the present study, we found that nonsegmental vitiligo patients with leukotrichia had significantly higher serum levels of IL-17A than patients without leukotrichia." (PMID 33968147, 2021). "In this study, we found that serum IL-17A level was significantly increased in patients with nonsegmental vitiligo compared to healthy controls, confirming the findings of studies." (PMID 33968147, 2021). "For example, secukinumab (IL‐17A inhibitor) application leads to new depigmentation onset in patients rather than halt vitiligo development in the clinical trial." (PMID 33200838, 2021). "First of all, the concentration of IL-17A was only measured in the serum, but not in the skin or follicles of the vitiligo patients." (PMID 33968147, 2021). "In this cross-sectional study, we evaluated the relationship between serum levels of IL-17A and the clinicopathological characteristics of Vietnamese individuals with nonsegmental vitiligo." (PMID 33968147, 2021). "We also found that serum IL-17A levels were negatively correlated with age in patients with vitiligo but not in healthy controls." (PMID 33968147, 2021). "MiR-133b was upregulated in lesional skin from nonsegmental vitiligo through targeting IL17 A/F." (PMID 36187493, 2022).
vitiligo (continued). "Furthermore, in a single-arm pilot study, the IL-17A inhibitor secukinumab failed to produce clinical results in the treatment of vitiligo and even worsened the condition in the majority of patients." (PMID 35884944, 2022). "In addition, serum IL-17A levels were higher in vitiligo patients with leukotrichia than in patients without it (P = 0.04)." (PMID 33968147, 2021). "We also found a negative correlation between IL-17A levels and age of onset in vitiligo patients." (PMID 33968147, 2021). "Furthermore, serum IL-17A levels were negatively correlated with age (r = −0.39, P = 0.004) and age of onset (r = −0.33, P = 0.016) in vitiligo patients but not in healthy controls." (PMID 33968147, 2021). "IFN-γ and IL-17A exerted no influence on the shedding of cell-associated GPNMB, whereas both decreased the GPNMB expression itself, possibly loosening the interaction between the keratinocytes and melanocytes to form the floating melanocytes in vitiligo." (PMID 32188902, 2020). "In this study, we could notobtain shave biopsies from vitiligo patients to phenotype IL-17A producing T cellsby FACS, but we do observe IL17A+ T cells in the dermal area of leading edgevitiligo biopsies, as well as CD8+ cells infiltrating the basal layer of theepidermis." (PMID 21541348, 2011). "Other groups have reported that IL10, IL13, IL17A, and IL21 are increased in vitiligo, though we did not observe this in our case series study." (PMID 33384688, 2020).
chronic obstructive pulmonary disease (75 papers, 2009 to 2025). A chronic and progressive lung disorder characterized by the loss of elasticity of the bronchial tree and the air sacs, destruction of the air sacs wall, thickening of the bronchial wall, and mucous accumulation in the bronchial tree. "Measuring 30 cytokines in 936 sputum samples from patients with chronic obstructive pulmonary disease, we observed significant increases (IL-17A, TNF-α, IL-1β, IL-10) between stable and exacerbation states." (PMID 38836471, 2024). "Azithromycin decreases the secretion of IL-4, IL-5, IL-13, and IL-17A from peripheral blood mononuclear cells in patients with chronic obstructive pulmonary disease (COPD)." (PMID 37357527, 2023). "Genetic deletion of IL-17A reduces alveolar type II cell apoptosis and thus alleviates chronic obstructive pulmonary disease." (PMID 36983002, 2023). "Cigarettes smoking and IL-17A contribute to chronic obstructive pulmonary disease (COPD), and have synergistical effect on bronchial epithelial cell proliferation." (PMID 34794427, 2021). "It is reported that a chromatin remodelling associated with IL-17A-mediated IKKα activity and histone H3 acetylation in Lys14 increase the TSLP mRNA transcription in bronchial epithelial cells during chronic obstructive pulmonary disease (COPD) pathogenesis." (PMID 33652749, 2021). "IL-17A is an important pro-inflammatory cytokine involved in the inflammatory response in chronic obstructive pulmonary disease (COPD)." (PMID 31964947, 2020). "IL-17A regulates airway inflammation, oxidative stress, and reduction of steroid sensitivity in chronic obstructive pulmonary disease (COPD)." (PMID 30291224, 2018). "IL17a is important in neutrophil inflammation in the exacerbation by NTHi of chronic obstructive pulmonary disease." (PMID 26611891, 2016). "When CCSPcre/K-rasG12D were induced with Chronic Obstructive Pulmonary Disease (COPD)-like inflammation, local production of IL17A recruited Gr1+ CD11b+ myeloid cells to the lung." (PMID 31921642, 2019). "Moreover, JKAP levels are lower in patients with chronic obstructive pulmonary disease; JKAP is also inversely related to pulmonary function and IFN-γ and IL-17A levels." (PMID 41458980, 2025). "IL-17A reportedly promotes increased expression of LCN2 in human neutrophils and remodeling of airway epithelium in patients with chronic obstructive pulmonary disease (COPD)." (PMID 39139502, 2024).
metabolic syndrome (75 papers, 2014 to 2026). A cluster of metabolic risk factors for CARDIOVASCULAR DISEASES and TYPE 2 DIABETES MELLITUS. "In parallel, metabolic syndrome has also been shown to independently increase postoperative recurrence risk, accompanied by elevated eosinophil counts and enhanced IL-5 and IL-17A expression, with recurrence risk rising proportionally with the number of metabolic syndrome components." (PMID 41011011, 2025). "Metabolic syndrome, characterized by metabolic disorders, plays a major role in this, with IL-17 a key factor in the clinical manifestations of metabolic syndrome." (PMID 38698841, 2024). "That study reported a lower serum IL-17A level among patients with metabolic syndrome compared to the controls." (PMID 30862094, 2019). "More comprehensive studies are needed to determine the relationship between epicardial adipose tissue and IL-17A more precisely among patients with metabolic syndrome." (PMID 30862094, 2019). "Another important finding of our study is that the IL-17A level was significantly greater among patients with metabolic syndrome compared to the control subjects." (PMID 30862094, 2019). "Serum interleukin 17A level was significantly greater in the metabolic syndrome group compared to the control group (2.9 ± 3.7 pg/mL vs. 0.1 ± 0.2 pg/mL, p < 0.001)." (PMID 30862094, 2019). "The main finding of our study was that the EATT and IL-17A level were higher among patients with metabolic syndrome compared to the control group." (PMID 30862094, 2019). "Our finding that the patients with metabolic syndrome had a higher IL-17A level also corroborates this notion." (PMID 30862094, 2019). "Additionally, the concentration of IL‐17A was 2.9 ± 3.7 pg/mL in metabolism syndrome, while 0.1 ± 0.2 pg/mL in control group." (PMID 39946217, 2025). "Thanks to its marked proinflammatory properties, IL-17A may play an important role for the pathogenesis of the metabolic syndrome." (PMID 30862094, 2019). "Similarly, serum IL-17A levels were significantly elevated in the metabolic syndrome group compared to the control group statistically (p < 0.001)." (PMID 30862094, 2019). "Hence, it can be concluded that the concentration of IL-17A in the blood may be a predictor of cardiovascular disease or metabolic syndrome." (PMID 35277002, 2022). "We detected an increased serum IL-17A and a positive correlation between serum IL-17A level and EAT, which may be interpreted as an indirect sign of increased coronary artery disease risk among a metabolic syndrome population." (PMID 30862094, 2019). "Unlike that study, we detected higher IL-17A level among patients with isolated metabolic syndrome." (PMID 30862094, 2019).